PF4 (platelet factor 4)
Diseases named in the same sentence as PF4 in open-access papers (continued):
Sharing a sentence is not in itself a finding about the gene and the disease.
COVID-19 (continued). "PF4 and its role in HIT as well as in pathologies seen in COVID-19 patients define a potential therapeutic option of using blocking antibodies in the treatment of COVID-19." (PMID 33050376, 2020). "In addition, sera from COVID-19 patients contain pro-NETotic factors such as RANTES (CCL5) and platelet factor 4 (PF4), likely secreted by hyperactivated platelets and their precursor megakaryocytes, which are known to harbor SARS-CoV-2." (PMID 41596316, 2026). "Notably, the heightened suppressive function of HLA_DR+ Tregs in severe COVID-19 patients, with interactions between PF4 and CXCR3, contributed to the homeostasis of HLA_DR+ Tregs in severe COVID-19 patients." (PMID 40114921, 2025). "It is also noteworthy that long-term follow-up of the patient, particularly during the COVID-19 vaccination period, showed no recurrence of anti-PF4 antibodies after administration of a dose of the ChAdOx1 nCoV-19 adenoviral vector vaccine." (PMID 41302191, 2025). "No significant increase in anti-PF4/H antibody levels was observed during COVID-19 regardless of disease severity." (PMID 40123654, 2025). "However, we observed an enhanced interaction between PF4 from CD14+ monocytes and CXCR3 from HLA_DR+ Tregs in COVID-19 patients, suggesting that PF4-CXCR3 plays an important role in maintaining homeostasis and suppressive function of Tregs." (PMID 40114921, 2025). "Our study found no significant increase in anti-PF4/H antibodies in COVID-19 or after vaccination, including in SID patients." (PMID 40123654, 2025). "First, IgG anti-PF4/H levels were assessed in sera from 122 controls2003-2010 patients who were never vaccinated against COVID-19." (PMID 40123654, 2025). "None of the positive anti-PF4/H antibodies detected in COVID-19 or vaccination cohorts induced platelet activation, measured by soluble P-selectin levels and flow cytometry-based on platelet microvesicle generation." (PMID 40123654, 2025). "This study shows no increase in anti-PF4/H antibodies in COVID-19 or after vaccination, including SID patients." (PMID 40123654, 2025). "We found that serum 25(OH)D level had a significant negative correlation with anti-PF4 level in mild COVID-19 patients." (PMID 39287233, 2024). "We observed a significant decline in anti-PF4/P antibody levels in convalescent patients, like what is observed in patients with HIT, VITT, or COVID-19, in whom antibody levels are transiently and acutely elevated under antigen exposure and inflammatory conditions, with a rapid decline in recovery." (PMID 38652559, 2024). "We found there was a significant negative correlation between anti-PF4 level and serum 25(OH)D level in mild COVID-19 patients." (PMID 39287233, 2024). "Serum 25(OH)D level had a significant negative correlation with anti-PF4 level in mild COVID-19 patients." (PMID 39287233, 2024). "Platelet-activating PF4-antibodies have been detected also in COVID-19-vaccinated individuals even without heparin exposure." (PMID 38540666, 2024). "We conclude that the synergy of high PF4 concentration, PF4/virus complexes, and PF4-antibodies or the synergistic COVID-HIT system majorly contributed to the development of unusual severe thrombotic thrombocytopenia in COVID-19 patients." (PMID 38540666, 2024). "It has been reported that healthy donor sera contain less than 1.0 μg/mL PF4, but PF4 concentration in the plasma of both severe and non-severe COVID-19 patients strongly increased even up to 30 μg/mL." (PMID 38540666, 2024). "It became clearer when a recent study detected anti-PF4 antibodies including IgG, IgM, and IgA in 95% of hospitalized COVID-19 patients, irrespective of prior heparin treatment." (PMID 38540666, 2024). "Fourthly, in this study, we are unable to confirm whether COVID-19 and VITT patients’ sera contain antibodies against PF4/SP complexes." (PMID 38540666, 2024). "Recently, PF4 antibodies were found in over 95% of unvaccinated hospitalized COVID-19 patients, independent of prior heparin treatment." (PMID 38140254, 2023).
COVID-19 (continued). "We found that EVs from COVID-19 patients carry CRP, PF4, and HMGB-1 on their surface, which may further fuel immunothrombosis." (PMID 38069209, 2023). "Another study reported that approximately 7% of individuals vaccinated against COVID-19 with adenovirus vector-based vaccines or mRNA vaccines had low titers of anti-PF4 Abs; however, these antibodies were not functionally active." (PMID 36851332, 2023). "Our data support these observations, since both, COVID-19 negative and COVID-19 positive sepsis patients had increased PF4 and D-dimer levels compared to healthy individuals." (PMID 36980378, 2023). "Regardless, to the best of our knowledge, plasma PF4 titers have not been studied in VITT nor COVID-19 patients." (PMID 37261122, 2023). "PF4 was increased in COVID-19 negative patients, while the confidence intervals overlapped with the control for COVID-19 positive patients." (PMID 36980378, 2023). "New assays allow to identify VITT-like anti-PF4 antibodies in these patients, which are related to severe immunothrombosis independent of heparin or (COVID-19) vaccination." (PMID 37834770, 2023). "The fact that VITT occurs mainly after vaccination with ChAdOx1 suggests that VITT-induced antibodies against PF-4 do not react to the COVID-19 spike protein but probably react to the adenoviral vector." (PMID 35892907, 2022). "It has been discovered that AstraZeneca COVID-19 vaccination increased the reactivity of VITT patients’ serum with platelets, implying the interactions between the vaccine and platelets or the vaccine and PF4." (PMID 35582622, 2022). "This study generally elicits findings that portray activation of IgG against PF4-heparin complex following ChAdOx1 COVID-19 vaccine in women of child-bearing age who had no significant associated medical history." (PMID 35368622, 2022). "Previously, conspicuously high antibody titres against platelet factor 4 (PF4)/Heparin have been found in COVID-19 sufferers, however without platelet-activating effect." (PMID 35184205, 2022). "Many scientists have been researching COVID-19, and they have found nonplatelet-activating and platelet-activating anti-PF4/heparin antibodies." (PMID 35582622, 2022). "Because PF4 is a major target of autoantibodies in COVID-19 vaccine-associated coagulopathies, lack of clear cross-reactivity of SARS-CoV-2 antibodies to PF4 again helps to explain the safety of the spike-protein-based vaccines." (PMID 36232795, 2022). "Finally, PF4, its contribution to HIT, and to pathologies in cases suffering from COVID-19 reflect a therapeutic alternative to using blocking antibodies for COVID-19 treatment." (PMID 36016187, 2022). "It has also been reported that almost 7% of COVID-19 vaccinated individuals (both adenovirus vector-based vaccines and mRNA vaccines) have low titers of PF4 antibodies, but these antibodies are not functionally active." (PMID 34887867, 2021). "While circulating levels of PF4 did not differentiate between severe and nonsevere COVID-19 cases, sP-selectin was higher among the severe COVID-19 group, in keeping with previous reports." (PMID 33596198, 2021). "Several studies report the presence of anti-PF4/heparin antibodies in COVID-19 patients, these antibodies can also be found without any history of heparin administration." (PMID 34443589, 2021). "•No significant increase in anti-PF4/H levels was observed after COVID-19 vaccination." (PMID 40123654, 2025). "•No significant increase in anti-PF4/H levels was observed in COVID-19 patients." (PMID 40123654, 2025). "AV COVID-19 vaccines may facilitate the formation of a pro-inflammatory and pro-thrombotic milieu in VITT, which supports the concept of raising plasma PF4 levels over a threshold to mount an anti-PF4 response (see Section “Platelet factor 4”)." (PMID 37261122, 2023).
COVID-19 (continued). "The exact role of PF4-mediated platelet-neutrophil interaction in COVID-19 was not investigated further albeit a single study on COVID-19 patients that reported elevated levels of both PF4 and RANTES (Regulated and Normal T cell Expressed and Secreted), a chemokine released from platelets." (PMID 37275917, 2023). "Recently, it was reported that COVID-19 patients might present with reactivity in PF4/heparin antigen tests without the presence of platelet-activating antibodies." (PMID 36131342, 2022). "PF4-dependent platelet-activating antibodies are transient in most patients with VITT; in addition, HIT ELISA reactivity alone has been directly associated with COVID-19 severity in a cohort of 65 hospitalized patients without any evidence of HIT/VITT." (PMID 35456110, 2022). "Therefore, anti-PF4 antibodies are likely not responsible for the thrombosis seen in COVID-19 patients and do not demonstrate cross reactivity with the Spike protein." (PMID 35371058, 2022). "Interestingly, COVID-19 patients tested positive in PF4/heparin antigen tests without evidence of platelet-activating antibodies in functional tests." (PMID 35619694, 2022). "This is supported by the observations that COVID-19 and HIT share many clinical similarities; COVID-19 patients are often exposed to heparin in the context of hospitalization; and a high proportion of COVID-19 patients test positive for anti-PF4/heparin antibodies on further testing." (PMID 35371058, 2022). "Although we used the baseline values of anti-PF4 antibodies of the participants as an internal control group, we did not include an independent control group of non-vaccinated healthy individuals with no history of prior COVID-19 as an external control group." (PMID 34358129, 2021). "In addition, anti-PF4–related non-platelet activating antibodies have been detected in patients with COVID-19 who were suspected of having HIT." (PMID 34358129, 2021). "Nonetheless, circulating PF4 levels could not differentiate between severe and nonsevere COVID-19 patient cohorts (p = 0.85)." (PMID 33596198, 2021). "Anti-PF4 antibodies were detected in 8.6% of COVID-19 patients but could not activate platelets." (PMID 35455346, 2022). "None of SLE patients, non-APS thrombotic patients, COVID-19 patients and HDs have been found positive for anti-β2-GPI/PF4." (PMID 41601650, 2026). "All VITT and none of the SLE, non-APS thrombosis, COVID-19 patients and HDs were positive for anti-β2-GPI/PF4." (PMID 41601650, 2026). "It includes different entities, such as VITT and anti-PF4-negative TTS, in subjects who had received mRNA-based COVID-19 vaccines." (PMID 40573981, 2025). "Notably, some studies have reported that anti-PF4 antibody detection may be influenced by factors such as altered antigenic complexes following SARS-CoV-2 infection (COVID-19) or vaccination, potentially leading to false-negative or atypical results in individual cases." (PMID 40717963, 2025). "Intriguingly, it has been reliably suggested that the pathophysiology of COVID-19 VITT is mediated by non-specific antibody responses, particularly PF4-reactive antibodies." (PMID 39656241, 2025). "Unlike the applied COVID-19 vaccines and most tested vectors, Ad34 and Ad80, as well as Ad5 vectors with deleted or chemically shielded hexon hyper-variable region 1 (HVR1), did not bind to PF4." (PMID 41509905, 2026). "Increase in PF4/CXCL4 in BAL from non-survivors might reflect both MK destruction in pulmonary vessels and platelet activation, shown to occur in COVID-19 patients." (PMID 35708858, 2022). "We found that molecules involved in platelet degranulation (CD9, platelet factor 4 (PF4)), aggregation, and activation [CD9, CLEC1B (also known as CLEC2)] were upregulated dramatically in COVID-19 EVs, while none of these proteins were detectable in EVs from healthy donors." (PMID 35820906, 2022).
COVID-19 (continued). "The human in vivo evidence that the anti-PF4 response in VITT is neither related to the spike protein nor to SARS-CoV2 came from data collected in a cohort of 11 patients with a history of VITT and subsequent COVID-19." (PMID 36351906, 2022). "Interestingly, we also detected the presence of anti-β2-GPI/PF4 antibodies in all 3 patients with VITT, but not in patients with COVID-19, including those with thrombophilic complications, suggesting that the thrombotic mechanism underlying VITT is different from that of COVID-19 infection." (PMID 41601650, 2026).
thrombosis (132 papers, 2011 to 2026). "Analyzing the possible association between the presence of autoantibodies and clinical manifestations, a significant association between positivity for anti-β2-GPI/PF4 antibodies and the development of venous thrombosis (p=0.032) was found." (PMID 41601650, 2026). "We propose a name of PF4‐associated immune thrombocytopenia and thrombosis (PITT) as an overarching term." (PMID 40298004, 2025). "In view of this, the term PF4‐associated immune thrombocytopenia and thrombosis (PITT) would seem a more appropriate umbrella term for these similar disorders." (PMID 40289696, 2025). "Vaccine‐induced immune thrombocytopenia and thrombosis (VITT) is one of several anti‐platelet factor 4 (anti‐PF4)‐associated immune thrombocytopenia and thrombosis (PITT) syndromes." (PMID 40298004, 2025). "Owing to her predisposition to develop thrombosis, her PF4 level was measured for the first time in 8 years." (PMID 39189244, 2024). "While platelet-activating anti-PF4 disorders cannot be excluded in this case, it is well known that they strongly associate with thrombosis." (PMID 39337907, 2024). "Cases of VITT have a high probability of positivity for anti-PF4 antibody, with a positive rate of 91%, but the causal relationship between thrombosis after mRNA vaccination and PF4 antibody is unclear and warrants further research." (PMID 38200562, 2024). "It is possible to check patients for a potential post-vaccination decrease in platelet count or thrombosis using an enzyme-linked immunosorbent assay (ELISA) or by using a PF4-enhanced platelet activation assay to detect antibodies against PF4." (PMID 38034236, 2023). "It was associated with atypically located cerebral and splanchnic venous thrombosis, abnormal platelet activation, and circulating autoantibodies, which attach themselves to the platelet-secreted protein, platelet factor 4 (PF4)." (PMID 38034388, 2023). "These defects were responsible for reduced thrombus formation under flow conditions ex vivo and protection against arterial thrombosis in platelet-specific GluN1 deficient (Grin1fl/fl-Pf4-Cre+) mice." (PMID 37252113, 2023). "An atypical SRA pattern with elevated anti‐PF4/H IgG titers seems associated with an increased risk of thrombosis in HIT." (PMID 35971886, 2022). "In most cases, antibodies against platelet factor-4/polyanion complexes play a pathogenic role, leading to thrombosis with thrombocytopenia syndrome (TTS) and sometimes a severe clinical or even fatal course." (PMID 35184205, 2022). "Neutrophil activation promotes HIT venous thrombosis by enhancing neutrophil-endothelial cell adhesion and neutrophil clot infiltration, in which the PF4-NET-HIT antibody complex causes thrombosis to spread." (PMID 34926629, 2021). "Anti-PF4 antibody-mediated immunothrombosis gained major attention in 2021, when it was identified as cause of a rare but severe adverse reaction to adenoviral vector-based COVID-19 vaccines: vaccine-induced immune thrombocytopenia and thrombosis (VITT)." (PMID 40236285, 2025). "Those complications were associated with unusual cerebral and splanchnic venous thrombosis, and circulating autoantibodies directed against anti-platelet factor 4 (PF4), a protein secreted from platelets, leading to the designation: Vaccine-Induced Immune Thrombotic Thrombocytopenia (VITT)." (PMID 38034388, 2023). "IgG-positive PV patients encountered thromboses in 57.1% suggesting anti-PF4/heparin IgG may contribute to higher risk for thrombosis in MPN." (PMID 28698883, 2017). "However, the memory B cells responsible for producing pathogenic anti‐PF4 antibodies and thrombosis may still be present in the pigs, as the recurrence of clinical signs occurs specifically around Days 108–112 of pregnancy, rather than over a period typical of common infectious diseases." (PMID 39869452, 2025). "The resolution of both anti-PF4-mediated immune-thrombosis and NETosis was achieved by intravenous immunoglobulin (IVIG) treatment." (PMID 40573981, 2025).